CRAT37 (cervical cancer-associated transcript 37 )
Gene: Long non-coding RNA gene on chromosome 15 (91,373,681 to 91,653,390, forward strand). Ensembl gene ENSG00000258551.
Diseases named in the same sentence as CRAT37 in open-access papers:
CRAT37 is named in the same sentence as 3 diseases in open-access papers, as found by Europe PMC text mining. Sharing a sentence is not in itself a finding about the gene and the disease. The quoted sentences say what the papers report.
cervical cancer (1 paper, 2022). A primary or metastatic malignant neoplasm involving the cervix. "Rs11853125 is located at the region between Cervical Cancer-Associated Transcript 37 (CRAT37) and Solute Carrier Organic Anion Transporter Family Member 3A1 (SLCO3A1)." (PMID 35299963, 2022).
prediabetes (1 paper, 2022). "We found two susceptibility loci in MRPS6/SLC5A3 genes associated with 2hPG, six loci in LINC01648, MATN1, CRAT37, and SLCO3A1 genes associated with HbA1C, and five loci in TRPM3/TMEM2 and MLYCD/OSGIN1 correlated to BMI in Hainan prediabetes." (PMID 35299963, 2022).
tumor (1 paper, 2020). "Meanwhile, the other 13 lncRNAs (AC008781.2, HULC, AC100839.1, CRAT37, LINC01198, LINC01482, SMAD1‐AS2, TH2LCRR, DISC1‐IT1, ABCC5‐AS1, NFIA‐AS1, AC007431.1, AC012494.1) were up‐regulated and hypomethylated in CC tumor group which confirmed our previous MethylRad sequencing results." (PMID 32869528, 2020).